P4HA3 (prolyl 4-hydroxylase subunit alpha 3)
Diseases named in the same sentence as P4HA3 in open-access papers (continued):
Sharing a sentence is not in itself a finding about the gene and the disease.
tumor (22 papers, 2016 to 2026). "To confirm the anti-tumor role of P4HA3 deficiency by enhancing anti-tumor immune procedure in cancers, we performed migration, invasion and EdU experiments in vitro and mouse tumor models in vivo." (PMID 39504328, 2024). "Enrichment analysis results indicated that high expression of P4HA3 was associated with metabolic-related pathways, the metabolic disorder of host and cancer cells are crucial for understanding tumor origin and development." (PMID 39504328, 2024). "In the present study, P4HA3 deficiency can strengthen anti-tumor immunity by increasing PD-1 expression and decreasing Ki-67 expression in BRCA." (PMID 39504328, 2024). "In this study, we firstly explored the significant role of P4HA3 deficiency in promoting anti-tumor immunity and immunotherapeutic limitation in various of cancers." (PMID 39504328, 2024). "The survival analysis results suggest that overexpression of P4HA3 is associated with poor prognosis in tumor patients." (PMID 37035741, 2023). "Here, we will evaluate the correlation of P4HA3 expression with tumor TMB, MSI, MMR Gene, CNA, and mutational status." (PMID 37035741, 2023). "Moreover, P4HA3 deficiency inhibited the proliferation, migration and invasion abilities of tumor cells, and promoted anti-tumor immunotherapy of PD-1/PD-L1 inhibitor." (PMID 39504328, 2024). "The results of this analysis suggest that P4HA3 is associated with tumor stemness." (PMID 37035741, 2023). "In summary, P4HA3 may be involved in tumor development by regulating genetic mutation status or epigenetic modifications." (PMID 37035741, 2023). "Thus, P4HA3 is closely associated with tumor-associated immune cells and functional status." (PMID 37035741, 2023). "qPCR analysis revealed that CSAD, IL4I1, and P4HA3 were significantly upregulated in tumor specimens, whereas PSAT1 expression was notably reduced in ccRCC tissues (p<0.05)." (PMID 41584585, 2025). "The radiogenomic characteristics of NCOA7 low expression share common features with Prolyl 4-Hydroxylase Subunit α 3 (P4HA3), specifically ill-defined margins and a more advanced tumor stage according to the AJCC." (PMID 40282346, 2025). "In PDX mouse model of TNBC, we found P4HA3-knocked down markedly inhibited PDX tumor growth, P4HA3-knocked down also inhibited the expression of P4HA3 and Ki-67 in IHC sections." (PMID 39504328, 2024). "More importantly, our research provided a significant perspective in the important role of P4HA3 in anti-tumor immunotherapy and CAFs infiltration." (PMID 39504328, 2024). "Compared with normal controls, the expression levels of P4HA1, P4HA2, and P4HA3 were significantly higher in tumor tissues, particularly in HNSC." (PMID 38806556, 2024). "This study aimed to investigate the relationship between P4HA3 expression and anti-tumor immunity and its prognostic value in pan-cancer." (PMID 39504328, 2024). "The top 20 targets highly upregulated in tumor compared to all NT (ranked according to the log2(FC) T vs CT) include transcripts encoding for COL11A1, TNC, PTK7, and P4HA3." (PMID 39681068, 2024). "Our findings provide new insights into the functional role of P4HA3 in human cancer, highlighting the potential mechanisms by which P4HA3 affects the tumor microenvironment and cancer immunotherapy." (PMID 37035741, 2023). "The analysis showed that P4HA3 was significantly positively correlated with different tumor stemness indices such as DMPss, DNAss, ENHss, and EREG-METHss in KIPAN, PRAD, GBM, LGG, LUAD, KIRC, KIRP, and SARC." (PMID 37035741, 2023). "Based on the CCLE dataset, the expression levels of P4HA3 in different tumor cell lines were analyzed." (PMID 37035741, 2023). "Many previous studies have shown that P4HA3 promotes tumor cell growth, proliferation, and metastasis in HNSC by activating the EMT process." (PMID 37035741, 2023).
tumor (continued). "The results show that P4HA3 was differentially expressed in tumor tissues and corresponding normal tissues, especially in the brain, lung, esophagus, liver, gallbladder, stomach, intestine, thyroid, bladder, and bone." (PMID 37035741, 2023). "The role of P4HA3 in DNA methylation, copy number variation (CNV), mutational status, tumor mutational burden (TMB), and microsatellite instability (MSI) was also analyzed." (PMID 37035741, 2023). "As an enzymic subunit of prolyl 4-hydroxylase, P4HA3 was critical for the stability of collagen and its dysregulation would directly activate the invasiveness potential of tumor cells." (PMID 36816030, 2023). "We also examined the effect of P4HA3 knockdown on tumor growth and metastasis using a mouse xenograft model." (PMID 34168290, 2021). "P4HA3 expression in tumor tissues (primary and recurrent tumors) was higher than that in non-tumor tissues." (PMID 34168290, 2021). "Further analysis of differences in the gene expression levels of ADAM12, MMP1, SERPINE1, PLOD3, and P4HA3 between tumor and adjacent normal tissues in 18 cancer types from TCGA were examined." (PMID 34121340, 2021). "Thus, the deficiency of P4HA3, which functions mainly as a mediator of collagen synthesis, consistently reduced tumor malignancy both in vitro and in vivo, suggesting that collagen synthesis pathways and extracellular matrix modification is an important regulator of tumor progression." (PMID 32539762, 2020). "We found that knockdown of either DYNLT3 or P4HA3 significantly reduced the tumor malignant properties in both cell lines, in terms of cell proliferation, migration, and anchorage-independent colony formation efficiency in soft agar." (PMID 32539762, 2020). "A recent study showed that P4HA3 appears to be a target effector of the TGFβ pathway mediating the tumor/migration-promoting activity of TGFβ." (PMID 32539762, 2020). "In contrast to the knockdown of DYNLT3, the knockdown of P4HA3 significantly inhibited tumor progression and metastasis in vivo in terms of tumor volume, tumor weight, and total flux of luciferase activity in the lungs." (PMID 32539762, 2020). "Taken together, these data suggested COL6A6 elevated inhibited tumor growth and metastasis in PA via interacting with P4HA3 and blocking the PI3K-Akt pathway." (PMID 31627190, 2019). "Recently, several studies found that P4HA3, as an oncogene in multiple tumors, was a positive correlation with tumor growth and poor survival." (PMID 31627190, 2019). "In the tumor P4HA3 mRNA was detected in the stroma compartment in three out of five tumors and it was undetectable in the cancer cell compartment of all tumors." (PMID 27809802, 2016). "Our study indicates that P4HA3 depleted can promote anti-tumor immunity and P4HA3 upregulation maybe a potential prognostic molecular." (PMID 39504328, 2024). "The aberrant expression of P4HA3 might modulate tumor metabolic activity, immune cells and EMT processes in cancers." (PMID 39504328, 2024). "In the further, we will conduct more experiments to verify the viewpoint that P4HA3 may be an attractive therapeutic target by blocking pro-tumor CAFs and reversing immunosuppression and chemoresistance in the TME." (PMID 39504328, 2024). "Among 33 types of cancers, P4HA3 had generally different expression between different tumors, further analysis showed that the expression of P4HA3 was correlated with the cells infiltration of the tumor microenvironment (TME)." (PMID 39504328, 2024). "Moreover, ccRCC with P4HA3 expression presents primary tumor size, ill-defined margins and more advanced tumor stage (American Joint Committee of Cancer), all features that are not present in ccRCC with GIMAP expression." (PMID 37895181, 2023). "In addition, the relationship between P4HA3 and the tumor immune microenvironment was further analyzed." (PMID 37035741, 2023).
tumor (continued). "This evidence, combined with our current findings, further demonstrates that P4HA3 may be involved in tumor progression in pan-cancer through multiple biological processes with EMT as the primary role." (PMID 37035741, 2023). "Therefore, in this study, we also evaluated the correlation between P4HA3 expression and tumor immune cell infiltration levels." (PMID 37035741, 2023). "P4HA3 is overexpressed in melanoma and promotes tumor proliferation and invasion." (PMID 37035741, 2023). "Secondly, the correlation of P4HA3 with immunomodulatory genes, immune checkpoint genes, RNA modification genes, immune cell infiltration, cancer-related functional status, tumor stemness index, DNA mismatch repair (MMR) genes and DNA Methyltransferase was examined." (PMID 37035741, 2023). "The results showed that the expression of P4HA3 was relatively similar in various tumor cell lines." (PMID 37035741, 2023). "shRNA-mediated P4HA3 knockdown significantly reduced the tumor volume in subcutaneous xenografts." (PMID 34168290, 2021). "Furthermore, the effects of COL6A6 interacted with P4HA3 on tumor growth and metastasis in PA were substantiated in vivo." (PMID 31627190, 2019). "Our data indicate an additional role for P4HA3 in the matrix-producing cells in the tumor stroma." (PMID 27809802, 2016). "Therefore, P4HA3 may serve as a promising biomarker for human cancer diagnosis, treatment, and prognosis and may predict the efficacy of anti-tumor immunotherapy response." (PMID 37035741, 2023). "As assessed by IHC, PRODH1 and P4HA3 (the enzymatic subunit of P4H involved in proline hydroxylation in collagen synthesis) were found in tumour gland-like structures and we confirmed epithelial localization by co-staining with wide-spectrum cytokeratin (wsKRT) in murine tumour sections." (PMID 28685754, 2017). "The results demonstrated that the abundance of DOHH, P4HA3 and MMP1 were higher in tumor cases than normal cases." (PMID 37957566, 2023). "Tumor volume and weight of mice injected with SW480 cells overexpressing miR-1266-3p or P4HA3 were detected." (PMID 35433237, 2022). "P4HA3, TNM (tumor, node, metastases) stage, pathological stage and age all correlated with OS rates." (PMID 35846138, 2022). "Further, knockdown of P4HA3 diminished TGF-β-dependent changes in amino acids, EMT, and tumor metastasis." (PMID 34168290, 2021). "Meanwhile, RT-qPCR assays revealed that ALDH6A1, FBP1, HAO2 and PSAT1 were markedly under-expressed in tumor tissues in exceeding 60% cases, and that TYMP, HK3, P4HA3, IL4I1, CYP26A1 and CPT1B were over-expressed in tumor tissues in exceeding 70% cases." (PMID 32737333, 2020). "We then assessed overall tumour expression of PRODH1 and P4HA3 via immunoblot and found that PRODH1 is over-expressed (sevenfold) in PDAC relative to control tissue while P4HA3 protein levels are unchanged." (PMID 28685754, 2017). "Future prospective research focusing on P4HA3 and TME could be useful for providing an immuno-based and metabolic-based anti-tumor therapeutic strategies." (PMID 39504328, 2024). "Expression of DOHH, P4HA3 and MMP1 was assessed with qRT-PCR in tumor cases and the normal cases." (PMID 37957566, 2023). "ROC analysis indicated differences in P4HA3 expression between tumor tissues and non-cancerous tissues." (PMID 35846138, 2022). "Next, we used ImmuCellAI to evaluate the immune infiltration score and the abundance of 24 immune cells from tumor tissues, and then calculated the multiple and single correlation coefficients of ADAM12, MMP1, SERPINE1, PLOD3, and P4HA3 with mRNA expression and immune infiltration score." (PMID 34121340, 2021). "In addition, EMT induces expression of angiogenic factors including MMPs43, suggesting that P4HA3 contributes to angiogenesis through EMT and, consequently, suppresses in vivo tumor growth." (PMID 34168290, 2021).
tumor (continued). "To further clarify the mechanism of COL6A6 regulated the growth and metastasis of PA cells, we assessed the effect of COL6A6 interacted with P4HA3 on the PI3K-Akt pathway, which plays an important role in regulating tumor development, tumor cells invasion and EMT." (PMID 31627190, 2019). "However, P4HA3 also exhibits traits such as larger primary tumor size and signs of infiltration, which are not observed in NCOA7 low expression." (PMID 40282346, 2025). "Finally, qRT-PCR revealed that the abundance of DOHH, P4HA3 and MMP1 were high in tumor cases, indicating the complex mechanism between the high expression of DOHH as a protective factor and the high expression of P4HA3 and MMP1 as the risk factors in the development of GC." (PMID 37957566, 2023). "More accurately, tumor stroma might play an important role in negative immunoregulation since the hub genes (i.e., CTHRC1, COL1A1, LOXL2, P4HA3, and FKBP10) related to immunosuppressive GO terms usually participate in collagen formation." (PMID 33791227, 2021).
cancer (12 papers, 2016 to 2024). A tumor composed of atypical neoplastic, often pleomorphic cells that invade other tissues. "All these data together suggested that high P4HA3 expression was widely associated with cancer proliferation and metastasis." (PMID 39504328, 2024). "Then, we analyzed the mutation frequency of 23 cancers by using SangerBox tool, the data showed that P4HA3 have relatively low mutation frequency in various of cancers." (PMID 39504328, 2024). "We found that P4HA3 expression level was positively associated with the number of infiltrating CAFs in various of cancers (appeared in at least 3 out 4 algorithms)." (PMID 39504328, 2024). "In human cancers, P4HA3 expression was significantly associated with five MMR genes, especially in LAML and THCA." (PMID 37035741, 2023). "The extracellular matrix protein, prolyl 4-hydroxylase subunit alpha 3 (P4HA3), has been implicated in various cancers." (PMID 35846138, 2022). "Combined metabolome and transcriptome analysis identified prolyl 4-hydroxylase α3 (P4HA3), an enzyme implicated in cancer metabolism, to be upregulated during TGF-β stimulation." (PMID 34168290, 2021). "We thus conclude that the ADAM12, MMP1, SERPINE1, PLOD3, and P4HA3 signature showed a close association with a pan‐cancer effect on prognosis and is related to ECM proteins in the TME which corresponding with immunologically “cold” cancer types." (PMID 34121340, 2021). "We integrated analyzed the function of P4HA3 among 33 types of cancers, and found that P4HA3 was associated with proliferation markers (PCNA and MKI67), EMT markers (VIM, TWIST1, SNAI1, SNAI2, FN1 and CDH2), extracellular matrix (ECM) markers (MMP9, MMP7, MMP2 and MMP14)." (PMID 39504328, 2024). "The results suggest that P4HA3 is associated with multiple immune cells in most cancers." (PMID 37035741, 2023). "P4HA3 has been shown to have an association with many different cancers." (PMID 35846138, 2022). "In addition, EMT is a crucial step of cancer cell migration and invasion, we focused on the possible associations between P4HA3 expression and classic EMT markers, such as Vimentin (VIM), TWIST1, Snail2 (SNAL2), Snail1 (SNAL1), Fibronectin1 (FN1), and N-cadherin (CDH2)." (PMID 39504328, 2024). "According to these results, we conducted that P4HA3 conferred malignant phenotypes to various of cancer cells via activating EMT, in the further, we will perform more experiments to verify this conjecture." (PMID 39504328, 2024). "To explore the possible biological role of P4HA3 in various of cancers, we used gene co-expression analysis to evaluate P4HA3 function and regulatory mechanism." (PMID 39504328, 2024). "We explored the relationship between DNA methylation and P4HA3 expression by using the gene set cancer analysis (GSCA) tool among different types of cancers." (PMID 39504328, 2024). "In various of cancers, P4HA3 expression was positively correlated with infiltrated central memory CD8+ T cell, central memory CD4+ T cell, Type 1 T helper cell, regulatory T cell, natural killer cell, macrophage and mast cell." (PMID 39504328, 2024). "The role of P4HA3 in cancer development is not well known and lacks comprehensive analyses among human cancers." (PMID 39504328, 2024). "Genetic and DNA methylation alterations, survival analysis and proteins co-expression analysis of P4HA3 in cBio Cancer Genomics Portal, TCGA, GSCA and TIMER2.0." (PMID 39504328, 2024). "Our results showed that P4HA3 upregulation was correlated with DNA copy number amplification and methylation in various of cancers." (PMID 39504328, 2024). "Based on above results that P4HA3 is generally high expression in various of cancers, we explored the genetic alteration and epigenetic regulation of P4HA3 from different databases." (PMID 39504328, 2024). "Based on the GEPIA dataset, we found P4HA3 expression was positively correlated with advanced cancer stages in KIRC (P = 0.0118), LUAD (P = 0.0233), and STAD (P = 0.0396)." (PMID 39504328, 2024).